EGFR (epidermal growth factor receptor)
Diseases named in the same sentence as EGFR in open-access papers (continued):
Sharing a sentence is not in itself a finding about the gene and the disease.
cancer (continued). "Downstream substrates of EGFR have been found responsible for drug resistance meanwhile activation of PI3K/AKT pathway is essential for cancer cell survival." (PMID 28626426, 2017). "Transforming growth factor alpha (TGFα) is a natural ligand for the EGFR, which plays a central role in cancer development." (PMID 28473665, 2017). "It is possible that upregulation of EGFR give cancer cells new survival mechanisms that are clinically actionable." (PMID 28489591, 2017). "The development of agents with binary activities, such as boron carriers for BNCT and anti-EGFR activities, represents a novel approach to cancer treatment." (PMID 28832537, 2017). "Our data demonstrate that miRNAs with an AAGUGC motif in their seed sequence increase both cancer cell proliferation and sensitivity to EGFR inhibitors." (PMID 27477696, 2017). "Because EGF–EGFR signaling can promote either cell survival or death, it is an oversimplification to state that EGFR activity increases survival in cancer cells." (PMID 27935858, 2017). "By inhibiting EGFR, the cancer cell re-acquired a working apoptosis pathway responsive to DNA damage." (PMID 28887666, 2017). "E-cadherin/β-catenin complex can activate PI3K/AKT pathway and epidermal growth factor receptor (EGFR) for the survival and proliferation of cancer cells." (PMID 28587302, 2017). "Because the frequency of allelic emergence of this mutation is less than 0.1% in most cases, it is thought that first-generation EGFR TKI-responsive tumors acquire resistance by the selection of a minor population cancer cells expressing T790M." (PMID 29140271, 2017). "A series of studies on EGFR, detailed below, has proven the importance of EGFR in preclinical and clinical sciences, thus establishing a basis for cancer therapeutics." (PMID 29140271, 2017). "The major downstream regulators determining cancer stemness are derived from either EGFR signaling or another drug-resistant pathway; therefore, they have been considered as therapeutic targets to overcome the acquired resistance from cancer stemness." (PMID 28787001, 2017). "One such example of a receptor tyrosine kinase that is frequently altered in a variety of cancers including GBM is the epidermal growth factor receptor (EGFR), a member of the ErbB family of receptor tyrosine kinases." (PMID 28410196, 2017). "Particularly the activation of EGFR / ErbB1 and ErbB2 has been shown to be important in the progression of different human cancers, and decorin has been shown to interact with both of them." (PMID 28653173, 2017). "They found that inhibition of PI3K, AKT, or mTOR decreased PD-L1 expression in EGFR-mutated NSCLC cell lines, which was similar to our finding in HER2-amplified cancer cell lines." (PMID 28969039, 2017). "EGFR constitutes an important druggable target in cancer therapy, as evidenced by the approval status of the monoclonal antibodies cetuximab and panitumumab, as well as the kinase inhibitors gefitinib and erlotinib." (PMID 27803950, 2017). "Dacomitinib (PF-00299804) is a tyrosine kinase inhibitor (TKI), which is predicted to only be effective in cancers where the targets of this drug (EGFR, ERBB2, ERBB4) are abnormally active." (PMID 28394918, 2017). "The importance of EGFR signaling pathway in cancer biology and its potential as a therapeutic target in human cancer is well established." (PMID 29137301, 2017). "This Q-dot system can also be applied to cancer treatment research by loading therapeutic anti-cancer siRNAs into the anti-EGFR Apt-QLs." (PMID 28842588, 2017). "Although the role of EGFR in cancer cells is well studied, the effects of secreted EGFR transported by exosomes are less understood." (PMID 28393839, 2017). "As mentioned in the results section, PLD network involves proteins such as LPAR4, LPAR6, HCRTR1, and GRM5, as well as pathways like EGF/EGFR SP, which their roles have been proven in initiation and progression of several cancers." (PMID 29062084, 2017).
cancer (continued). "Recently, many studies have focused on the overexpression of cyclin D1 proto-oncogene (cell cycle regulatory protein) and EGFR (growth factor of epithelial cells) in cancers and the literature in this field is quite abundant." (PMID 29354245, 2017). "Because EGFR has a vital role in cancer development, many studies have focused on anti-EGFR treatment." (PMID 28445956, 2017). "CS substrates also promoted the expressions of EGFR/Myc target genes that modulate cancer proliferation." (PMID 28367998, 2017). "There is emerging in vitro and in vivo experimental evidence suggesting superiority of SYM004 to first-generation anti-EGFR antibodies, such as cetuximab and panitumumab, in a wide range of cancers." (PMID 28978055, 2017). "HER3 thus plays an important role in maintaining EGFR- and HER2-driven cancers and mediating resistance to EGFR- and HER2-targeted therapy." (PMID 28899363, 2017). "The mutations of RAS (KRAS and NRAS), IDH2, EGFR, and PI3K are clinically relevant and well associated in many other cancers." (PMID 28900470, 2017). "In recent years, EGFR testing is standard for advanced treatment-naïve patients in most cancer centres or big comprehensive hospitals in China, and more and more patients with EGFR mutations have been treated with first-line EGFR-TKI therapy." (PMID 28079142, 2017). "EGFR has been a major target of interest in cancer treatment for years due, in part, to it's over expression in a wide variety of human cancers (e.g. lung, head and neck, breast, colon, pancreas)." (PMID 29069801, 2017). "Treatment of NSCLC patients sensitive or resistant to EGFR inhibitors should attempt to impact not only oncogene-driven cancer cell growth but also the EMT phenotype in early NSCLC development stages." (PMID 29262566, 2017). "An EGFR up-regulation has been represented in a large range of tumors, characterized more aggressive phenotype of these cancers compared to those with a low or normal expression." (PMID 28415812, 2017). "Only 3D cancer models exhibited a significant sensitivity towards inhibition of EGFR signaling, whereas the 2D cultures were only weakly responding to the drugs." (PMID 29296175, 2017). "In the past two decades, more than 7 EGFR inhibitors have been clinically used for cancer treatment." (PMID 28460454, 2017). "CAS 879127-08, a specific inhibitor of epidermal growth factor receptor (EGFR), is highly toxic to cells, and it induces cancer cell apoptosis." (PMID 29168788, 2017). "The v-erbB oncogene was found to contain recombinations of the transmembrane and cytoplasmic domains of the EGFR, implicating EGFR aberrations to cancer." (PMID 28513565, 2017). "The EGFR gene is overexpressed in several human cancers and is considered a reasonable anticancer therapy target." (PMID 28832537, 2017). "This gives new opportunities to develop novel therapeutic strategies to treat cancers that rely on EGFR signaling networks and autophagy." (PMID 28338617, 2017). "PE38, which lacks an intrinsic cell-binding domain, binds to EGFR-expressing cancer cells via the TGFα moiety within the recombinant toxin." (PMID 28473665, 2017). "The epidermal growth factor receptor (EGFR) plays a critical role in normal development and in human cancer." (PMID 29229958, 2017). "EGFR is well-studied model in resistance to targeted cancer therapy, and consequently, is a good system to validate the full scope of the framework." (PMID 28436422, 2017). "In this review, we discuss the roles of EGFR in cancer development, therapeutic strategies for targeting EGFR, and the resistance mechanisms to EGFR-targeted therapies (EGFR TKIs and anti-EGFR mAbs), with a focus on cancer therapies for individual patients." (PMID 29140271, 2017). "Aberrant activation of EGFR and other ErbB receptor family members in cancer is primarily attributed to increased gene copy numbers or gain-of-function mutations in the genes encoding these receptors." (PMID 29229958, 2017).
cancer (continued). "Our study highlighted the great possibilities offered by these filled and functionalized CNTs, which were able to internalize more efficiently into EGFR positive cancer cells." (PMID 28198410, 2017). "At least nine cancer therapeutics [monoclonal antibodies (mAbs) and small-molecule tyrosine kinase inhibitors (TKIs)] targeting EGFR and/or HER2 are currently in clinical use." (PMID 28881753, 2017). "This suggests that the coadministration of unlabelled targeting ligand with radiolabelled PEGylated NP offers a promising strategy for targeting EGFR-positive cancer and for minimising liver uptake." (PMID 29071190, 2017). "The epidermal growth factor receptor (EGFR) is one of the most well-studied signaling pathways in cancer progression." (PMID 28435746, 2017). "Pre-targeting of PEG engagers induce endocytosis of PEGylated nanocarriers into EGFR+ TNBC cancers leading to enhanced antitumour efficacy of PEG-modified therapeutic agents in vitro and in vivo." (PMID 28593948, 2017). "Our data implicate that EGFR inhibitors in addition to combination with PTX can be used to overcome acquired chemotherapy resistance in MUC1-positive cancer." (PMID 28796259, 2017). "Another interesting receptor is the epidermal growth factor receptor (EGFR) which has been the subject of numerous targeted cancer therapies." (PMID 28218708, 2017). "Nuclear EGFR contributes to promote an aggressive phenotype of cancer cells and correlates with poor prognosis and chemo-resistance in different cancer types, including NSCLC." (PMID 28415726, 2017). "It has been reported that CUR suppresses the expression of epidermal growth factor receptor (EGFR) and estrogen receptors, which are cancer-relevant growth factor." (PMID 28155567, 2017). "To prepare the diabody-type bispecific antibody library, we used 4 anti-T-lymphocyte Fvs with affinity for CD3 or CD28, and 13 anti-cancer Fvs with affinity for members of the EGFR family (EGFR, HER2–4) 18, 22–39." (PMID 28588218, 2017). "LRBA interacts with multiple important signal transduction pathways including EGFR and its deregulation in several cancer types has been shown to facilitate cancer cell growth." (PMID 28650955, 2017). "EGFR is abnormally expressed and activated in many cancer cells, and initiates signal transduction cascades that promote cell division, migration and angiogenesis." (PMID 29142206, 2017). "With in-depth studies of genesis and cancer related signal pathway, epidermal growth factor receptor (EGFR)-dependent pathway was revealed to play important roles in the development and progression of epithelial cells in NSCLC patients." (PMID 28430623, 2017). "Autophagy induced by the tyrosine kinase-independent EGFR also supports cancer cell survival, which provides a mechanism for cancer cells to escape toxicity from EGFR-TKIs." (PMID 28338617, 2017). "In preclinical models of HNSCC, in addition, knockdown of c-Met has enhanced sensitivity of cancer cells to anti-EGFR agents." (PMID 29348891, 2017). "We performed a retrospective matched-pair case-control study from 3 cancer centers, including 44 SQC and 44 ADC patients with EGFR mutation who were treated with EGFR-TKI." (PMID 28591695, 2017). "In this study, we developed anti-epidermal growth factor receptor (EGFR) antibody-conjugated MBs (EGFR-MBs) and evaluated their capacity to enhance anti-cancer drug toxicity in vitro and in vivo." (PMID 28938010, 2017). "Compared to GE11 conjugated TSL, Fab̕-coated TSL (Fab̕-TSL) bound to the EGFR overexpressed cancer cells more specifically and efficiently as shown by flow cytometry and live cell imaging analyses." (PMID 29552041, 2017). "EGFR binds Amphiregulin (AREG) that is overexpressed in several cancers such as colon, breast and lung." (PMID 28600504, 2017). "After cancer recurrence, the PD-L1 was further up-regulated in patients with chemotherapy and EGFR-TKI therapy but decreased in the patients with anti-PD-1 therapy." (PMID 29254184, 2017).
cancer (continued). "EGFR and c-Met corroborate the downstream signaling pathways in cancer cells in that c-Met and EGFR activate many of the same downstream signaling molecules." (PMID 28086832, 2017). "Our goal was to use defined cancer cell lines and an EGFR/CD3-bispecific tool BiTE® in order to establish the basic characteristics and mechanism of a bystander killing effect." (PMID 28837681, 2017). "Amongst them, the EGFR pathway is used reiteratively for organ and tissue formation, and when dysregulated can lead to cancer and metastasis." (PMID 28678789, 2017). "These mutant KRAS or BRAF-driven cancers show a poorer response to chemotherapy and are negatively indicated for treatment with EGFR inhibitors." (PMID 28640835, 2017). "For instance, CMTM7, another member of the CMTM family, has been shown to inhibit cancer cell growth by inhibiting oncogenic EGFR signalling and the Akt signalling pathway." (PMID 29213215, 2017). "As a consequence of the binding, EGFR turnover, stability and signaling, as well as cancer cell motility were affected." (PMID 28038470, 2017). "EGFR overexpression has been widely reported in a number of cancers, including breast, ovarian, bladder, non-small-cell lung (NSCLC), colorectal cancers, and other tumors." (PMID 28057023, 2017). "To date, it has been well established that miR-7 directly targets many oncogenic factors and is involved into multiple cancer-related signalling pathways, including EGFR, IRS-1/2, Raf1, Pak1, Ack1, PA28-gamma, IGF1R, PIK3CD and mTOR32–38." (PMID 28710406, 2017). "EGFR is of immediate medical and biological importance due to its well-established roles in developmental biology, tissue homeostasis, and cancer." (PMID 28038470, 2017). "EGFR is overexpressed in SKBR3, but has relatively low expression in BT-474 (~62% of 1018 cancer cell lines in the GDSC database had higher EGFR expression than BT-474)." (PMID 28481952, 2017). "All three cell lines express EGFR and TLR4 receptors, although at different levels; notably, MCF-7R has lost E-cadherin expression and acquired Vimentin, while showing higher levels of EGFR and alpha-enolase, all features of cancer cell aggressive phenotype." (PMID 28630480, 2017). "The inhibition of EGFR and its related proteins is considered as a standard approach in cancer investigations." (PMID 28218686, 2017). "Overexpression of the EGFR is correlated with prognosis of several kind of cancer and activated EGFR signals via the RAS, ERK1/2 and PI3K/Akt pathways." (PMID 28038457, 2017). "On the other hand, upregulation or hyperactivation of epidermal growth factor receptor is considered as a prognostic marker in many cancers, especially in non-small-cell lung cancer (NSCLC)." (PMID 29072684, 2017). "GE11-Ori-Se NPs were found to induce cancer cell apoptosis by inducting reactive oxygen species (ROS) production, activating mitochondria-dependent pathway, inhibiting EGFR-mediated PI3K/AKT and inhibiting Ras/Raf/MEK/ERK pathways." (PMID 29019267, 2017). "We analyzed data of patients with adenoCA (WT EGFR) and squCA collected from the Taiwan Cancer Registry database." (PMID 27835914, 2017). "YM155 had a stronger inhibitory capacity against cancer stemness by simultaneously inhibiting EGFR autophosphorylation and G9a expression." (PMID 28787001, 2017). "Abrogation of EGFR signaling through pharmacological or genetic inhibitors suppressed the self-renewal growth and expansion of cancer stem cells." (PMID 28460475, 2017). "While BRAF and EGFR inhibitors can produce dramatic responses temporarily, acquired resistance inevitably occurs in lung and other cancers." (PMID 28145866, 2017). "After high-temperature sealing, SWCNTs were covalently functionalized with the monoclonal antibody (mAb) Cetuximab (Erbitux®) targeting the epidermal growth factor receptor (EGFR), overexpressed on several cancer cells." (PMID 28198410, 2017).
cancer (continued). "The recent clinical introduction of anti-EGFR agents (i.e. Cetuximab) for treatment of advanced HNSCC has emphasized the potential of EGFR as a target for anti-cancer therapy." (PMID 28841839, 2017). "Our results provide an example of EGFR deregulation in cancer through silencing of components of the nuclear import pathway." (PMID 29229958, 2017). "A potential candidate is the epidermal growth factor receptor (EGFR), which has been shown to be overexpressed and/or amplified in many human cancers." (PMID 28367377, 2017). "Conversely, EGFR signaling down-regulation-responsive genes were correlated with “miR-1 high” cancer samples." (PMID 28537886, 2017). "Of the human ErbB family members, EGFR functions as a critical mediator of tumor progression in several cancer types." (PMID 27902463, 2017). "Cancer-associated mutations in KRAS (10–30%), EGFR (10%) and BRAF (3%) in NSCLC patients are common." (PMID 28806950, 2017). "As the EGFR is expressed on a wide variety of cells, and is important for tissue homeostasis, off-target side effects of current EGFR inhibitors used in cancer treatment are common and can often be severe." (PMID 28970798, 2017). "To this end we stably expressed HRASG12V in the EGFR-positive, cetuximab-sensitive cancer cell lines A431 and Difi." (PMID 28507280, 2017). "Epidermal growth factor receptor (EGFR) has been shown to mediate the hypoxia‐induced cellular proliferation in some cancer cell lines." (PMID 28330951, 2017). "MEK inhibition in EGFR or ERBB2-driven cancers however is complicated, as it can lead to higher PI3K/AKT activation." (PMID 28513565, 2017). "Inhibition of SK-BR-3 or A-431 cancer target cell line proliferation in the presence of hTM and CM IgA antibodies targeting Her2 and EGFR, respectively, was shown." (PMID 28952521, 2017). "To evaluate the molecular mechanisms involved in the ability of LA to lower cancer cell viability, we ascertained that LA triggers the phosphorylation of EGFR, ERK and c-Jun in both SkBr3 and Ishikawa cells." (PMID 28924490, 2017). "We demonstrated that HGF or HGF-producing fibroblasts conferred resistance to EGFR targeting therapy by reactivation of pro-survival pathways in cancer cells, including ERK and AKT activation." (PMID 28420162, 2017). "In NSCLC, c-MET (MET) receptor tyrosine kinase has been associated with the development of resistance to EGFR tyrosine kinase inhibitors (TKIs) in various EGFR-mutant cancers." (PMID 29156837, 2017). "The epidermal growth factor receptor (EGFR) is a pivotal regulator of cell proliferation and progression, and widely expressed in several human cancer types (DEL)." (PMID 26461472, 2017). "In vitro experiments showed that 111In-EGF-Au-PEG targets EGFR-positive cancer cells (MDA-MB-468): >11% of radioactivity was internalised after incubation for 4 h." (PMID 29071190, 2017). "ERRFI1 is a negative regulator of EGFR family members, including EGFR, HER2 and HER3; all have been implicated in cancer." (PMID 28358873, 2017). "On the contrary, in patients with EGFR wild-type (WT) cancers, RRs and survival were significantly lower with gefitinib- compared to platinum-based chemotherapy in the IPASS study." (PMID 28424775, 2017). "TGF-α is a natural ligand for the EGFR, which is overexpressed in many tumors and plays a central role in cancer development by promoting cell proliferation and angiogenesis." (PMID 29387062, 2017). "For instance, as a classical PTP, DEP1 inhibits cancer cell proliferation by directly dephosphorylating of EGFR (epidermal growth factor receptor) in the cytoplasm." (PMID 28747184, 2017). "The epidermal growth factor receptor (EGFR) signaling pathways are altered in many cancers contributing to increased cell survival." (PMID 28338617, 2017).